POMC (proopiomelanocortin)
Diseases named in the same sentence as POMC in open-access papers (continued):
Sharing a sentence is not in itself a finding about the gene and the disease.
adenoma (351 papers, 2008 to 2026). A neoplasm arising from the epithelium. "USP8-mutated adenomas showed higher level of POMC, CDC25A, MAPK4 but lower level of CCND2, CDK6, CDKN1B than USP8-wild-type tumors." (PMID 38862897, 2024). "Since corticotroph adenomas harboring USP8 mutations are scarcely methylated at the first promoter, adenomas of Cushing disease are likely to utilize the first promoter to transcribe the POMC gene." (PMID 36834633, 2023). "A further pathogenic mechanism for ACTH-secreting adenoma tumorigenesis is represented by the increased transactivation of the proopiomelanocortin gene." (PMID 35054858, 2022). "In fact, we and others observed different molecular signatures in adenomas carrying USP8 variants compared to USP8-wildtype adenomas, and this carried over into increased POMC synthesis and ACTH secretion and changes in intracellular signalling." (PMID 32183012, 2020). "Loss of either Brg1 or histone deacetylase 2 can lead to GC resistance in ACTH-secreting adenomas, since Brg1 stabilizes the interaction between GR and histone deacetylase 2 to suppress proopiomelanocortin gene transcription." (PMID 35054858, 2022). "In primary cultures of ACTH-secreting human, canine, and murine adenomas, POMC mRNA was significantly suppressed by 63%–95% following treatment with gefitinib." (PMID 33841328, 2021). "Hypomethylation of the promoter of POMC, which encodes the precursor of ACTH, leads to the occurrence of corticotropin-secreting adenomas." (PMID 33574795, 2020). "This has been reinforced by their lower expression of both the corticotroph transcription factor, TBX19, POMC, and some adenomas showing poor and immature differentiation." (PMID 33066652, 2020). "We also investigated the expression of TSP‐1 in ACTH‐secreting adenoma and its effects on the expression of POMC, VEGF, Ki67 and MMP9." (PMID 31016850, 2019). "Incubation with CRH brought about an increase in POMC in the majority of adenomatous specimens, in agreement with studies on some 10 ACTH-secreting adenomas." (PMID 27220856, 2017). "Altogether, it appears that glucocorticoid suppression of both GRα and CRH-R1 is preserved in human corticotrope adenomas whereas glucocorticoid-mediated POMC modulation is variably altered." (PMID 27220856, 2017). "Previous research has primarily focused on pituitary ACTH-secreting adenomas, revealing alterations in transcription factors such as Tpit (also known as TBX19) and Pitx1, which regulate the expression of proopiomelanocortin (POMC), the precursor molecule for ACTH." (PMID 40002253, 2025). "Testicular receptor 4, an orphan nuclear receptor, has been shown to affect the binding of GR to the proopiomelanocortin promoter, and, thus, an increased expression of this molecule is thought to play a role in causing GC resistance in ACTH-secreting adenomas." (PMID 35054858, 2022). "Therefore, ACTH-secreting adenomas with a USP8 mutation displayed higher expression of the EGFR, and increased mRNA transcription of proopiomelanocortin (POMC), which is the precursor of ACTH." (PMID 33537004, 2020). "Both mutations enhance the promoter activity and transcription of the ACTH precursor, the proopiomelanocortin (POMC) gene, and are potential therapeutic targets for the excess secretion of ACTH in corticotropin-secreting adenomas." (PMID 33574795, 2020). "The methylation of POMC, FGFR2, RASSF1A, LGALS3, and apoptosis-related factors plays a potential role in the development of corticotropin-secreting adenomas." (PMID 33574795, 2020). "Objective of the present study was to report on constitutive and CRH- and dexamethasone-regulated POMC, CRH (CRH-R1), and glucocorticoid receptor (NR3C1) gene expression in a large series of human corticotrope adenomas." (PMID 27220856, 2017). "In fact, POMC increased from 20 to 500 % over baseline during CRH stimulation, even up to 14-fold in one adenoma." (PMID 27220856, 2017).
adenoma (continued). "In adenomas, LIF promotes proopiomelanocortin (POMC) synthesis, which mediates HPA (hypothalamic-pituitary-adrenal) axis response to stress." (PMID 26329521, 2015). "As regards ACTH synthesis, we did not observe differences in POMC expression between male- and female-excised adenomas both in unchallenged wells and after CRH/dexamethasone incubation." (PMID 32183012, 2020). "Moreover, we demonstrate that protein level PCSK1N, a well described inhibitor of PCSK1-mediated processing of POMC, was significantly increased in SCA, suggesting an additional mechanism responsible for the impaired POMC processing in the silent adenomas." (PMID 33066652, 2020). "Similar discrepancies have been reported during pharmacological challenges and support previously expressed hypotheses suggesting different regulatory mechanisms for POMC expression and ACTH secretion in corticotrope adenomas." (PMID 27220856, 2017). "Interestingly, the magnitude of POMC increase was not correlated with CRH receptor abundance, a finding which dovetails with data obtained at immunohistochemistry showing that CRH-R1 staining density in adenomas is not proportional to the ACTH response to CRH." (PMID 27220856, 2017).
depression (245 papers, 2006 to 2025). "The POMC gene, which regulates stress and mood, is linked to depression and suicidal tendencies when dysregulated." (PMID 39940809, 2025). "Previous work demonstrated that β-END differentially affected anxiety and depression, highlighting the importance of further studies of the interactions between depression, POMC rs2071345 polymorphisms, and alcohol dependence." (PMID 35592377, 2022). "Some individuals with POMC or LEPR deficiency experienced mild-to-moderate depression at the time of trial enrollment." (PMID 35123544, 2022). "The POMC gene had a highest degree of 41, encoding the adrenocorticotropin hormone (ACTH) peptide, which brought our attention to major depressive disorders and the regulation of hypothalamic–pituitary–adrenal (HPA) axis function." (PMID 27917343, 2016). "Clinical studies have shown selective epigenetic alterations on the POMC gene of adolescents who suffer from depression and self-injuries." (PMID 38263257, 2024). "Contrary to POMC, rodent models of depression reported lower levels of NPY in plasma, cerebral spinal fluid, frontal-limbic regions, and ARC." (PMID 38263257, 2024). "This suggests that POMC-ARC is a key hub regulating depression, including hypophagia and anhedonia." (PMID 40362394, 2025). "Consequently, levels of CRH, POMC, ACTH, and cortisol could be treated as biomarkers with potential translational use in depression and anxiety." (PMID 34440536, 2021). "Adults with major depressive disorder (MDD) have higher plasma levels of POMC, and their responses to antidepressants depend on the presence of certain POMC haplotypes." (PMID 38263257, 2024). "Intermittent prenatal exposure to MDMA has been associated with increased pro-opiomelanocortin (POMC) and corticosterone levels in the brain of adult offspring; interestingly, no behavioral effects on depression or anxiety behavior were observed." (PMID 31777665, 2019). "A recent study found that in major depressive disorder and in persistent depressive disorder, specific single nucleotide polymorphisms and haplotypes in genes related to the corticotrophin-releasing hormone (CRHBP, CRHR1) and melanocortins (POMC) predicted the non-responder status." (PMID 31507525, 2019).
pituitary tumor (245 papers, 2005 to 2026). A benign or malignant neoplasm affecting the pituitary gland. "In this study, we aimed to further investigate whether the CaMKK/CaMKIV pathway similarly underlies CRH-induced POMC expression in ACTH-producing AtT20 pituitary tumor cells, broadening the understanding of calcium-dependent mechanisms in ACTH production." (PMID 40453274, 2025). "These gene expression similarities are intriguing given that the POMC KO mouse pituitary tumors appear to develop from melanotrophs, whereas human NFPAs originate from gonadotrophs." (PMID 32591776, 2020). "Correspondingly, endogenous POMC processing in a mouse pituitary tumor cell line, AtT20, as demonstrated by the presence of intermediates, was attenuated in the absence of Sel1L." (PMID 29457782, 2018). "Pituitary tumors have been reported in the intermediate lobe in Rb heterozygous mice and in POMC-specific conditional Rb heterozygous mice in which the reporter gene was restricted to the intermediate and anterior lobes." (PMID 30147673, 2018). "Thus, expression of the simian virus 40 (SV40) large T antigen under the control of the proopiomelanocortin (POMC) gene promoter induced the formation of pituitary tumors arising from the intermediate lobe." (PMID 25136513, 2014). "Although EGFR is expressed in other lineages of aggressive pituitary tumors, our findings suggest that EGFR signaling induces E2F1-mediated POMC transcription and corticotroph adenoma pathogenesis." (PMID 30147673, 2018). "Transcriptomic differences between corticotroph tumors and non-functioning pituitary tumors revealed overexpression of POMC, which was attributed to the hypomethylation of the POMC promoter." (PMID 40257628, 2025). "As further evidence of the importance of the pituitary clock, circadian expression of pituitary POMC and PRL mRNA was observed in cultured murine pituitary tumor cell lines (AtT20, GH3 and GH4C1), and their expression correlated to the circadian proteins (PER-2 for POMC, and CLOCK for PRL)." (PMID 32272677, 2020). "Additionally, genes known to be related to pituitary tumor aggressiveness, such as securin (PTTG1) and fibroblast growth factor receptor 4 (FGFR4), are also differentially expressed in the POMC KO mouse tumors." (PMID 32591776, 2020). "Excess circulating POMC, the precursor of the stress hormone, adrenocorticotrophic hormone (ACTH), is most commonly documented in patients with pituitary tumours but also in patients with non-pituitary tumours, particularly SCLC." (PMID 26848743, 2016). "Although the POMC processing pathway to produce ACTH is complicated by the requirement of prohormone convertases and mature secretory vesicles, some non-pituitary tumors may not be sufficiently differentiated to generate this pathway." (PMID 38035072, 2023).
Anxiety (184 papers, 2007 to 2026). Intense feelings of nervousness, tension, or panic often arise in response to interpersonal stresses. "In their study, offspring behaviors were also affected by PAE, leading to the development of increased stress and anxiety linked with epigenetic changes in several stress-regulatory genes, including POMC." (PMID 38539304, 2024). "Although the functions of POMC neurons are mainly to control appetite and energy metabolism, an association between POMC neurons and anxiety has also been reported." (PMID 38116320, 2023). "Results indicated that the POMC rs2071345 polymorphism significantly moderated anxiety symptoms associated with alcohol dependence." (PMID 35592377, 2022). "Specifically, compared to adults with CC homozygote of POMC rs2071345, those with the T allele reported more anxiety symptoms when experiencing more severe alcohol withdrawal as measured by alcohol problem severity." (PMID 35592377, 2022). "Further, we found that the POMC rs2071345 is unexpectedly associated with the severity of anxiety symptoms during acute alcohol withdrawal, which previously has not been reported." (PMID 35592377, 2022). "Fourth, the current study only estimated the interactions between the POMC rs2071345 polymorphism with alcohol problem severity on anxiety symptoms, which is another limitation." (PMID 35592377, 2022). "As such, our study provides new evidence for the moderating function of the POMC polymorphism in the association between current stress as measured by the severity of alcohol dependence during withdrawal and anxiety symptoms." (PMID 35592377, 2022). "The present study provides preliminary evidence for distinct G × E interactions such that the POMC rs2071345 polymorphism interacted with alcohol dependence on male problem drinkers' anxiety during acute alcohol withdraw." (PMID 35592377, 2022). "We examined the interactions between POMC rs2071345 polymorphism with alcohol dependence on anxiety symptoms during acute alcohol withdrawal, and further explored the nature of POMC rs2071345 × alcohol dependence by testing two competing models: diathesis-stress vs. differential susceptibility." (PMID 35592377, 2022). "Moreover, it is reported that the POMC gene expression is associated with anxiety-like behavior in those that experienced maternal deprivation." (PMID 35592377, 2022). "Thus, fetal alcohol exposure -induced POMC deficiency contributes at least partly to the increased anxiety-like behaviors in FAE offspring of the male germline for multiple generations." (PMID 35143549, 2022). "In the most recent work by these investigators fetal alcohol-exposed rat offspring showed increased POMC methylation and reduced gene expression that was associated with increased plasma corticosterone response to restraint stress and increased anxiety-like behavior." (PMID 36285916, 2022). "First, to our knowledge, this study is the first to examine the G × E interactions on this POMC polymorphism, alcohol dependence severity and anxiety during acute alcohol withdrawal, providing preliminary evidence for the distinct G × E interactions on alcohol dependence and anxiety." (PMID 35592377, 2022). "Thus, POMC deficiency can promote body weight gain, impair coloration pattern, and alleviate anxiety-like behaviors in mice, humans, and zebrafish." (PMID 35937837, 2022). "Interestingly, selective loss of Kalirin isoforms in POMC-Cre mice produces a similar reduction in anxiety-like behavior." (PMID 28535798, 2017). "Next, in the anxiety model, POMC rs2071345 polymorphism significantly moderates the association between severity of alcohol dependence and anxiety symptoms during acute alcohol withdrawal, confirming the hypothesis we proposed and supporting the diathesis-stress theory." (PMID 35592377, 2022).
Anxiety (continued). "Alenina and Bader reported that ACE2 overexpression in the hypothalamus inhibits corticotropin-releasing hormone synthesis and consequently decreases POMC and corticosterone release, which in turn suppresses the stress response and anxiety." (PMID 37575318, 2023). "The observed effects involved increased gene methylation of the POMC gene (proopiomelanocortin gene which is active in the stress-regulation axis) and its reduced expression, increased corticosterone response, and elevated anxiety in behavioural testing." (PMID 36672861, 2023). "In contrast with the increase in Ucn 2 levels, musclin decreased POMC levels and induced anxiety-like behaviors compared to that in vehicle-treated mice." (PMID 38116320, 2023). "Anxiety is often accompanied by dysregulation of the hypothalamus–pituitary–adrenal axis and increased levels of proopiomelanocortin (POMC) and corticosterone." (PMID 37575318, 2023). "In conclusion, our data suggest that FAE induces heritable changes in POMC gene expression and affects the stress response and anxiety-like behaviors via epigenetic modifications for multiple generations via the male germline." (PMID 35143549, 2022). "Furthermore, all the indexes in the re-parameterized regressions indicated that the POMC rs2071345 polymorphism × environment (alcohol problem severity) interactions were consistent with the weak diathesis-stress model among male problem drinkers with anxiety symptoms." (PMID 35592377, 2022). "We conducted traditional hierarchical regression analysis to identify the interaction between the POMC rs2071345 genotype and alcohol dependence on anxiety." (PMID 35592377, 2022). "A previous study showed that postnatal ablation of POMC neurons decreased food intake and led to enhanced anxiety-like behavior." (PMID 36387867, 2022). "This study suggested that the SNP in POMC rs2071345 was associated with alcohol dependence in anxiety symptoms of male problem drinkers and further provided evidence in support of the diathesis-stress hypothesis of alcohol dependence in terms of anxiety symptoms." (PMID 35592377, 2022). "Conversely, the inhibition of A2AR in the anterior lobe of the pituitary hyperactivates the HPA axis, increasing proopiomelanocortin, adrenocorticotropic hormone, and consequently blood corticosterone levels, which characterizes the anxiety-related profile." (PMID 36355494, 2022). "Overall, our findings show that high-dose RIB induced depressive- and anxiety-like behavior and spatial memory impairment in mice, and highlight the involvement of the insulin-POMC-MEK-TCF7L2 pathway in the hippocampus." (PMID 33531473, 2021). "Recently, it has been shown that stress which results in anxious behaviour increases activation of POMC and AGRP in arcuate neurons, while ablation of POMC neurons in the hypothalamus creates a phenotype with increased anxiety-related behaviour on the EPM." (PMID 24027581, 2013). "The genes CCK, POMC, MCHR1, GABRA6, HTR2A and DRD2, which associated with heat score in at least one brain area, are known to modulate emotional states like anxiety and satiety or even sexual motivation." (PMID 21504592, 2011). "Furthermore, acute activation of the ventral DG by channelrhodopsin in proopiomelanocortin (POMC)-Cre mice suppresses anxiety-like behavior in the EPM." (PMID 39176381, 2024). "In addition to satiety signal, POMC neurons involves in psychological responses such as pain, anxiety, fear and locomotion as well as energy homeostasis by integrating afferent neural and metabolic signals with data on energy status of the body." (PMID 37415911, 2023). "Interaction between POMC rs2071345 and alcohol dependence on anxiety." (PMID 35592377, 2022). "Based on the metabolite–gene network analysis, RIB induced depressive- and anxiety-like behavior and spatial memory impairment might be mediated by the insulin-POMC-MEK-TCF7L2 pathway." (PMID 33531473, 2021).
Anxiety (continued). "Mic-1 KO mice might be expected to have reduced POMC expression, which could then result in reduced glucocorticoid secretion and the anti-anxiety phenotype observed in our Mic-1 KO mouse model." (PMID 28081177, 2017). "POMC neurons project from the ARC to the amygdale to mediate anxiety." (PMID 26629487, 2015). "These included genes expected to be related to estrous behavior as they influence states like socio-sexual behavior, anxiety, stress and feeding motivation (OXT, AVP, POMC, MCHR1), but also genes whose association with estrous behavior is novel and warrants further investigation." (PMID 21504592, 2011). "Finally, metabolite–gene network, qRT-PCR and western blot analysis showed that the insulin-POMC-MEK-TCF7L2 and MAPK-CREB-GRIN2A-CaMKII signaling pathways were respectively associated with RIB and MAN induced depressive/anxiety-like behavior and spatial memory impairment." (PMID 33531473, 2021). "Given that anxiety is a prominent phenotypic behavior in PWS, we investigate the role of the Magel2 gene, particularly in hypothalamic POMC neurons innervating the medial amygdala (MeA), in the behavioral phenotypes associated with Prader-Willi Syndrome (PWS)." (PMID 41321745, 2025). "The potential involvement of proopiomelanocortin (POMC), kisspeptin and MCH signalling in several brain functions, including the affective responses, anxiety mechanisms, memory consolidation, sleep generation and control of autonomic homeostasis has come into consideration." (PMID 32914264, 2020). "There were no significant main effects of POMC rs2071345 genotype on anxiety (p > 0.05)." (PMID 35592377, 2022).